ACHE (acetylcholinesterase (Yt blood group))
Diseases named in the same sentence as ACHE in open-access papers (continued):
Sharing a sentence is not in itself a finding about the gene and the disease.
Alzheimer disease (continued). "Notably, inhibition of AChE is currently the most common treatment strategy for the symptoms of Alzheimer disease (AD)." (PMID 29581965, 2018). "Despite this uncertainty, one strategy in designing AChE inhibitors for use in against Alzheimer’s disease, has been to incorporate binding both at the catalytic site (to spare acetylcholine) and at the peripheral site (to prevent facilitation of Aβ aggregation)." (PMID 28714881, 2017). "The major role of AChE is to catalyse the hydrolysis of acetylcholine (ACh) in cholinergic synapses, while BChE can hydrolyse ACh as well as other esters; nevertheless, it seems its concentration in brain is especially important at Alzheimer’s disease (AD)." (PMID 29135926, 2017). "Currently, AChE inhibitors are the gold-standard treatment for Alzheimer’s disease." (PMID 28574473, 2017). "Moreover, we performed an in vitro acetylcholinesterase (AChE) activity assay and an amyloid-β aggregation test to examine the biological properties of phellodendrine and berberine as therapeutic drugs for Alzheimer’s disease." (PMID 28574473, 2017). "Therefore, a new drug discovery for Alzheimer’s disease is required, with more attention to the AChE inhibition and less side effects." (PMID 28574473, 2017). "The inhibition of LOX and AChE by SlEOs could lead to useful strategies for the treatment of inflammatory and Alzheimer’s diseases and for natural insecticidal purposes." (PMID 28825692, 2017). "As Ceylon cinnamon bark and leaf demonstrated both AChE and BChE inhibitory activities consumption in daily life could increase the acetylcholine level and would be beneficial for management of Alzheimer's disease." (PMID 28951761, 2017). "In fact, AChE inhibitors (AChEIs) are used as gold standard treatment in Alzheimer disease (AD)." (PMID 28411556, 2017). "However, those authors focused on the synergistic effect of the three alkaloids and evaluated only AChE activity as a biological marker of Alzheimer’s disease." (PMID 28574473, 2017). "Therefore, currently BChE inhibitors such as cymserine analogues and the dual inhibitor of both AChE and BChE such as rivastigmine are used therapeutically for treating Alzheimer's disease and other related dementias." (PMID 28951761, 2017). "AChE inhibitors can increase the cholinergic transmission by blocking the degradation of ACh and are therefore considered to be a promising approach for the treatment of Alzheimer's disease." (PMID 27642355, 2016). "Based on our current findings, we anticipate that fucoxanthin might exhibit great therapeutic efficacy for the treatment of Alzheimer’s disease by acting on multiple targets, including inhibiting AChE and increasing BDNF expression." (PMID 27023569, 2016). "Thus, the most promising approach for symptomatic treatment of Alzheimer’s disease is to increase the synaptic levels of acetylcholine in the brain through inhibition of acetylcholinesterase (AChE)." (PMID 26760993, 2016). "Imperatorin alone may be useful in the treatment of disorders such as epilepsy, anxiety, depression, as an AChE inhibitor it has prospects in the therapy of Parkinson’s and Alzheimer’s diseases." (PMID 27453708, 2016). "It is well established that alteration in the levels of acetylcholine or AChE activity may affect the cholinergic transmission process and leads to learning and memory a deficit which imitates Alzheimer’s disease." (PMID 26400617, 2015). "Our results highlighted Thymus species as a rich source of natural antioxidants and AChE inhibitors that could be useful in preventing and treating Alzheimer's disease and other neurodegenerative disorders." (PMID 26351513, 2015). "AChE inhibition activities may prove of novel values in clinical trials for the treatment of Alzheimer’s disease." (PMID 25741457, 2015).
Alzheimer disease (continued). "Acetylcholinesterase (AChE) inhibitors show good therapeutic effects on myasthenia gravis, glaucoma, and Alzheimer's disease through reversible enzyme inhibition so as to increase the accumulation of acetylcholine in the synapse and then promote and prolong the function of acetylcholine." (PMID 25861364, 2015). "Tacrine (1,2,3,4-tetrahydroacridin-9-amine) is another synthetic drug which easily crosses the blood brain barrier and is used as a highly effective drug for ameliorating Alzheimer disease manifestation by inhibition AChE and by lower but still effective inhibition of BChE." (PMID 24893223, 2014). "The enzymolytic effect of ZER towards AChE (acetylcholinesterase) could be the basis for the development of ZER in the treatment of Alzheimer's disease." (PMID 25025076, 2014). "Additionally, acetylcholinesterase (AChE) is the target for many Alzheimer's dementia drugs which block the function of AChE but have some side effects." (PMID 25054066, 2014). "More generally, it can be suggested that gradual inhibition of AChE, such as treatment strategy in Alzheimer disease, or intoxication by AChE inhibitors present in environment, may be accompanied by gradual changes in MR abundance." (PMID 23861875, 2013). "Needless to say, inhibition of AChE is the most popular as the treatment strategy against Alzheimer’s disease (AD), which is characterized by reduction in the activity of the cholinergic neurons according to cholinergic hypothesis." (PMID 24381529, 2013). "Although we have shown that human fetal intestinal epithelial cells provide an easy system to test the cytotoxicity of AChE inhibitors, further efficacy studies need to be conducted in mouse and monkey models of Alzheimer’s disease before any new compound can be studied in human clinical trials." (PMID 23675513, 2013). "AChE and BChE are enzymes that degrade the neurontransmitter acetylcholine through hydrolysis and lead to Alzheimer’s disease; hence, such diseases might be prevented by inhibition of AChE and BChE." (PMID 22890173, 2012). "Hence, the AChE inhibitory effects of plant extracts indicate their potential in the development of natural therapeutics for Alzheimer's disease and related problems." (PMID 20668582, 2010). "Finally, a selective increase of AChE activity was detected in plasma from Alzheimer's disease (AD) patients compared to age and gender-matched controls." (PMID 20090844, 2010). "Similarly, many of the AChE inhibiting drugs used in the treatment of Alzheimer's disease, such as tacrine, physostigmine, and galantamine, display concentration-dependent, dual modulation of agonist activation of the α7-nAChR." (PMID 19287501, 2009). "While AchE levels are reduced early in Alzheimer's disease, BchE levels rise with disease; selective BchE inhibition may be useful to ameliorate cholinergic defect." (PMID 17096857, 2006). "Alzheimer's disease (AD) is characterized by multifactorial pathological processes, including cholinergic dysfunction and oxidative stress, highlighting the need for safer, multi-target interventions beyond current synthetic acetylcholinesterase (AChE) inhibitors." (PMID 41948388, 2026). "The investigations reported that these ultra-small NPs exhibited remarkable potential to inhibit AChE activity, highlighting important implications and firmly positioning the synthesized NPs as a promising candidate with considerable therapeutic potential in Alzheimer’s disease (AD) therapy." (PMID 40819011, 2025). "Particularly, since the drug rivastigmine is a dual cholinesterase (AChE, BChE) inhibitor, a recognized key therapeutic target of AD (and also PD), the development of rivastigmine hybrids appears to have remarkable advantages as potential anti-Alzheimer’s disease agents." (PMID 40867820, 2025).
Alzheimer disease (continued). "Acetylcholinesterase (AChE) plays a crucial role in nerve function and signal transmission, but excessive activity during aging can deplete acetylcholine (ACh), leading to impaired neural communication and serious illnesses like dementia and Alzheimer’s Disease (AD)." (PMID 40233108, 2025). "Alzheimer’s disease (AD) is a progressive neurodegenerative disorder marked by pathological features such as tau protein aggregation and hyperphosphorylation, chronic neuroinflammation, and cholinergic dysfunction mediated by acetylcholinesterase (AChE) and butyrylcholinesterase (BuChE)." (PMID 41045341, 2025). "In contrast, resistance exercise could reduce AChE activity in rats with Alzheimer's disease." (PMID 38532712, 2024). "Thus, we can conclude that these three compounds (CID 102267534, CID 15161648, CID 12441) may inhibit the activity of AChE and can be useful as a treatment for Alzheimer's disease." (PMID 39483377, 2024). "In addition, the capacity of nanoparticles to inhibit AChE and BChE shows that AC-AgNPs could be used to manage Alzheimer’s disease." (PMID 36903556, 2023). "Similarly, the phenolic and flavonoid contents of Elatostema papillosum showed significant antioxidant and inhibitory activity against AChE and butyrylcholinesterase (BChE) in Alzheimer’s disease, with IC50 values of 165.40 4.01 and 213.81 3.57 μg/mL, respectively." (PMID 36986610, 2023). "The AChE enzyme is involved in numerous noncholinergic physiological functions, such as promoting cell development and differentiation, participating in apoptosis and relating to pathogenic processes including Alzheimer’s disease and tumorigenesis." (PMID 35631766, 2022). "Finally, the assessment of AChE activity indicated that EPSR4 could be a valuable natural therapeutic for Alzheimer disease." (PMID 36005587, 2022). "Two enzymes, acetylcholinesterase (AChE) and butyrylcholinesterase (BChE), are involved in the of acetylcholine hydrolysis, decreasing its level in Alzheimer’s disease, and thus, prohibition of both enzymes is a well-established strategy for the alleviation of Alzheimer’s disease." (PMID 36295014, 2022). "The promising AChE and BChE inhibitory capabilities of our synthesised chromium oxide nanoparticles implies that such NPs could be used therapeutically in neurodegenerative illnesses, including Alzheimer’s disease." (PMID 36313367, 2022). "Inhibitions of AChE decrease the hydrolysis of ACh in the brain and increase cholinergic neurotransmissions which might be helpful in treating mild to moderate levels of Alzheimer’s disease." (PMID 33669503, 2021). "In addition, a very recent study reported that AChE inhibitor treatments are associated with lower mortality in patients with diabetes mellitus with Alzheimer's disease or patients with mixed-pathology dementia, with a specific benefit provided by galantamine or another AChE inhibitor—donepezil." (PMID 33776997, 2021). "In this regard, the use of drugs able to inhibit the enzyme AChE and hence, to increase the levels of ACh in the brain and to improve the cognitive functions has a clear, rational benefit in the treatment of neurodegenerative disorders especially Alzheimer’s disease (AD)." (PMID 33916760, 2021). "Acetylcholinesterase (AChE) and butyrylcholinesterase (BChE) are largely involved in the neural transmission of synapses and their inhibitors have been identified as targets in the treatment of neurodegenerative disorders, including Alzheimer’s diseases and myasthenia gravis." (PMID 34018093, 2021). "AChE is a well-known serine hydrolase that catalyzes the hydrolysis of the neurotransmitter acetylcholine into choline and acetic acid; inhibiting it would increase acetylcholine levels in the brain, enhancing cholinergic synapses in Alzheimer’s disease patients." (PMID 34941722, 2021).
Alzheimer disease (continued). "Therefore, the AChE enzyme has potential therapeutic uses in improving ACh levels in brain cells, in reducing various side effects, and in improving cognitive impairment, especially in advanced Alzheimer’s disease patients." (PMID 33488216, 2020). "Thus, this fluoroalkylketone intended for neuroimaging, could be of interest in palliative therapy of Alzheimer’s disease and protection of central AChE against organophosphorus compounds." (PMID 33260981, 2020). "Inhibition of AChE serves as a strategy for the treatment of Alzheimer disease (AD), senile dementia, ataxia, myasthenia gravis, and Parkinson disease, and it has been considered as a potential therapeutic approach to AD." (PMID 32957713, 2020). "Furthermore, the bioactivity evaluation assay showed that kadsuricoccins A and B have moderate AChE inhibitory activities with predicted lower toxicity as some pentacyclic triterpenoids, while the AChE was an important target for Alzheimer’s Disease (AD) and myasthenia gravis." (PMID 31597363, 2019). "Therefore, inhibition of AChE is a therapeutic approach in Alzheimer’s disease." (PMID 29881705, 2018). "Therefore, inhibition of AChE resulting in prevention of the normal breakdown of ACh, may compensate for depletion of Ach seen in Alzheimer's disease." (PMID 29881705, 2018). "Moreover, the neuroprotective potential of a methanol extract of C. fistula roots was demonstrated by its ability to inhibit acetylcholinesterase (AChE), which is considered a promising target for the treatment of neurodegenerative disorders like Alzheimer’s disease (Rajasree, Singh & Sankar, 2012)." (PMID 30023139, 2018). "Additionally, phenolic compound activities, acting as inhibitors of acetylcholinesterase (AChE), have also been revealed and were closely correlated with their structure and could be used as effective and safe Alzheimer's disease (AD) therapy." (PMID 30627570, 2018). "Indeed, AChE might contribute to Alzheimer’s disease (AD) pathogenesis through its ability to interact with amyloid β (Aβ) and to increase neuronal death, the amyloid burden and cognitive deficits in mice." (PMID 25853328, 2015). "Therefore, inhibition of AChE activity is the main therapeutic approach for Alzheimer's disease." (PMID 25705233, 2015). "The cholinergic concept of Alzheimer’s disease (AD) was initially resulted from postmortem studies of the brain, which ultimately led to the development of new drugs based on the inhibition of the key enzymes acetylcholinesterase (AChE) and butyrylcholinesterase (BChE)." (PMID 26530857, 2015). "Molecular hybridization of flavonoids with carbamate moieties led to novel compounds with potent AChE and MAGL inhibition, providing a promising multi-target strategy for Alzheimer's disease treatment." (PMID 40395797, 2025). "This compound exhibited a strong affinity for inhibiting AChE and MAO-B in the nervous system of mice, and it also mitigated the cognitive impairment induced by scopolamine in Alzheimer's disease in mice." (PMID 39800464, 2025). "Despite recent significant advancements, the development of effective dual inhibitors targeting AChE and MAO-B in the treatment of Alzheimer’s disease remains challenging." (PMID 40733241, 2025). "Additionally, enhancing cholinergic neurotransmission through supplementation with AChE inhibitors, such as Donepezil, which is used to treat symptoms of Alzheimer’s disease, could be considered as a therapeutic approach to improve cognitive performance in people with T1DM." (PMID 41023469, 2025). "AChE inhibition of Lamiaceae species has been related to central effects, since its higher activity may imply increased levels of acetylcholine and, consequently, improvements of cholinergic neurotransmission that is relevant in the management of Alzheimer’s disease." (PMID 40732993, 2025).
Alzheimer disease (continued). "Eplerenone treatment improved memory and reduced AChE activity and neuroinflammation in an STZ-induced Alzheimer’s model, indicating potential cognitive protection through MR antagonism in Alzheimer’s disease models." (PMID 39997334, 2025). "Astaxanthin also displayed acetylcholinesterase (AChE) inhibitory activity, with an IC50 value of 297.99 μg mL−1, which is comparable to galantamine (4.11 μg mL−1), a standard treatment for Alzheimer’s disease." (PMID 39767994, 2024). "Since these compounds, beside AChE inhibitory activity, often exhibit additional pharmacological properties, especially antioxidants, they could be applied in multi-target strategies for combating the onset and progression of Alzheimer’s disease and other neurological conditions." (PMID 38337955, 2024). "In comparison, the synthetic drug, donepezil hydrochloride, commonly used for treating mild to moderate forms of Alzheimer’s dementia, served as a positive control in the test and exhibited an IC50 value of 12.40 ± 1.35 nM against AChE." (PMID 38611464, 2024). "The compound is known for its dual action in Alzheimer's Disease (AD), with IC50 values of 37.1 and 31.8 uM for AChE and MAOB, respectively." (PMID 38790018, 2024). "Therefore, the characterization of BC could be used as a pharmaceutical agent for the treatment of cholinergic neurotoxicity-associated neurovascular disorders such as developmental toxicity, vascular dementia, and Alzheimer’s disease due to its AChE and AP inhibitory actions." (PMID 37298835, 2023). "A multi-target activity 3D-QSAR model against acetylcholinesterase (AChE), serotonin transporter (SERT), beta-secretase 1 (BACE1) and glycogen synthase kinase-3 (GSK3β) was built to towards new therapeutics for Alzheimer’s disease." (PMID 36770990, 2023). "Two neurotransmitter-degrading enzymes (AChE and BChE) and the β-amyloid formation enzyme (BACE-1) were investigated to control Alzheimer’s disease." (PMID 38231711, 2023). "However, most of the isolated alkaloids with outstanding AChE inhibitory activity belong to the class of lycodine, which have two nitrogen atoms in the structure, such as the well-known huperzine A, which has great potential in the treatment of Alzheimer’s disease." (PMID 35893381, 2022). "Hippeastrum stapfianum ethanol extract (EE) can potentially lead to a new option for Alzheimer’s disease treatment due to the ability to activate PPAR receptors selectively, inhibit AChE, and present antioxidant capacity under the conditions evaluated." (PMID 36432907, 2022). "When this amine is a bulky amine as a N,N-dibenzyl(N-ethyl)amine fragment, several compounds of a studied series proved to act on three relevant targets in Alzheimer’s disease: σ-1 receptor (σ1R), BACE1 and AChE." (PMID 34771164, 2021). "Acetylcholinesterase (AChE) and lipoxygenase (LOX) play important roles in the progress of Alzheimer’s disease." (PMID 34200696, 2021). "In the mouse model of Alzheimer’s disease induced by scopolamine, MYR effectively reduced the impairment of learning and memory ability of mice through its AChE inhibitory ability." (PMID 33192493, 2020). "Acetylcholinesterase (AChE) and beta-secretase (BACE-1) are the two crucial enzymes involved in the pathology of Alzheimer’s disease." (PMID 32785161, 2020). "Acetylcholinesterase (AChE) and β-secretase (BACE-1) have become attractive therapeutic targets for Alzheimer’s disease (AD)." (PMID 32899576, 2020). "Furthermore, both essential oils were tested to evaluate their inhibitory activity on acetylcholinesterase (AChE) and butyrylcholinesterase (BChE), two enzymes important as pharmacological targets in the design of drugs active against neurodegenerative diseases such as Alzheimer’s disease." (PMID 31731807, 2019). "Our research gave a clue to search for new agents based on AChE and PARP-1 dual-inhibited activities to treat Alzheimer's disease." (PMID 30427217, 2019).